CST3 (cystatin C)
Diseases named in the same sentence as CST3 in open-access papers (continued):
Sharing a sentence is not in itself a finding about the gene and the disease.
acute coronary syndrome (17 papers, 2013 to 2025). Signs and symptoms related to acute ischemia of the myocardium secondary to coronary artery disease. "Recent studies have described cystatin C as a prominent predictor of cardiovascular diseases (CVD) that is significantly associated with high risk of cardiovascular outcomes in acute coronary syndrome (ACS)." (PMID 31317040, 2019). "We found that the leukocyte Rho kinase activity and serum Cystatin C were high in acute coronary syndrome patients, and were independent influencing factors of cardiovascular events in ACS patients." (PMID 32664054, 2020). "The leukocyte Rho kinase activity and serum Cystatin C are high in acute coronary syndrome patients, and are the independent influencing factors of cardiovascular events in ACS patients." (PMID 32664054, 2020). "This study was designed to investigate the effects of leukocyte Rho kinase activity and serum Cystatin C (Cys C) on cardiovascular events in patients with acute coronary syndrome (ACS)." (PMID 32664054, 2020). "Creatinine and Cystatin C are both an index of renal function, and Cystatin C has been shown to predict outcomes in patients with acute coronary syndrome." (PMID 28881821, 2017). "The aim of this study was to evaluate the predictive value of cystatin C (CysC) and estimated glomerular filtration rate (eGFR) regarding vascular lesions and their severity in patients with acute coronary syndrome (ACS)." (PMID 28143410, 2017). "Various studies found that cystatin C is also an important prognostic factor of a poor outcome in patients with acute coronary syndrome." (PMID 29254149, 2017). "Serum BTP levels, in addition to cystatin C concentrations, positively correlated with all-cause mortality risk in 226 patients diagnosed with non-ST-segment elevation acute coronary syndrome with a median follow-up period of 859 days." (PMID 38786272, 2024). "Recent studies have shown that the triglyceride glucose index (TyG) and cystatin C (CysC) are closely related to cardiovascular disease, but there is limited research on the prognosis of patients with acute coronary syndrome (ACS) after percutaneous coronary intervention (PCI)." (PMID 39257901, 2024). "Previous studies reported that cystatin C was associated with an increased risk of death and combined events in patients with non-ST elevation acute coronary syndrome, and this association was be regarded for its excellent representativeness of renal function." (PMID 35392813, 2022). "In this study, we have established a relationship between rIMT and biomarkers (creatinine, cystatin C and MPO) which have been suggested to be indicative of poor prognosis in populations with acute coronary syndrome." (PMID 28881821, 2017).
anemia (17 papers, 2016 to 2025). A reduction in the number of red blood cells, the amount of hemoglobin, and/or the volume of packed red blood cells. "Conversely, the role of the CNV on anemia risk and cystatin C is likely driven by a combined effect of the CNV on adiposity and EA, and other factors on which matching was performed." (PMID 39332408, 2024). "ACR measurements were significantly associated with anemia, acidosis, hypoalbuminemia, hyperphosphatemia, hyperkalemia, hypercholesterolemia and higher cystatin C levels." (PMID 27276392, 2016). "Markers of renal impairment (i.e. elevated cystatin C, phosphate, and urea) and indicators of anemia and macrocytosis (i.e. red blood cell enlargement) were also associated with MDD incidence." (PMID 34234104, 2021). "In the Cox multivariate analysis, anemia (HR 3.184 95% CI 1.855–5.465, p = 0.000) was significantly related to all-cause mortality, with adjustment for age, COPD, hematocrit, urea nitrogen, cystatin C, and LDL-C." (PMID 33304931, 2020). "Additionally, other possible biomarkers including anemia, C-reactive protein, and cystatin C have been identified." (PMID 37096248, 2023). "Anemia (HR 2.883, 95% CI 1.738–4.784, p = 0.000) and urea nitrogen [HR 1.072 (per 1 mmol/L), 95% CI 1.003–1.146, p = 0.042] were significantly associated with MACEs, when adjusting for age, COPD, hematocrit, cystatin C, creatinine, total cholesterol, and LDL-C." (PMID 33304931, 2020). "Although kidney function plays an important role in the development or persistence of anemia, serum creatinine or cystatin C was not available in this study." (PMID 38503801, 2024). "Patients with anemia had greater prevalence of DKD, higher levels of urinary albumin-to-creatinine ratio (UACR), serum creatinine, BUN, urine α1-MG, urine β2-MG, urine NAG/Cr, hsCRP, Cystatin C, homocysteine and lower eGFR, as compared to the patients without anemia." (PMID 36755908, 2023).
kidney injury (17 papers, 2013 to 2026). Trauma to the kidney. "When it was immediately estimated within 24 hours after admission for early detection of kidney injury, hence, serum or urine, cystatin C was very valuable.In addition, it was found that serum cystatin C was associated with the recovery, death, or renal replacement therapy of kidney injury." (PMID 36589822, 2022). "This threshold of increased serum cystatin C was obtained by a previous study to be an early marker for contrast-induced kidney injury." (PMID 37899762, 2023). "A study in a Chinese population suggested that the eGFR equation combined with cystatin C is superior to eGFR based on creatinine in early detection of kidney injury, and CKD-EPICysC is more sensitive to detect kidney injury and predict kidney outcome." (PMID 35321070, 2022). "Another marker of glomerular kidney injury that has been studied is cystatin C. It is an endogenous marker of renal dysfunction; in fact, it is a more adequate marker of GFR, rather than a primary AKI biomarker." (PMID 24265821, 2013). "Additionally, serum Cystatin C within 24 h of admission appears to be a marker for predicting acute kidney injury in CAP patients." (PMID 40547131, 2025). "Furthermore, KIM-1 and cystatin-C are more sensitive and accurate than standard biomarkers for early identification of gentamicin-induced kidney injury." (PMID 37237729, 2023). "The renal KIM-1, cystatin C and GST levels were evaluated in order to appraise the functional renal status among the experimental groups and detect the presence of kidney injury." (PMID 41011155, 2025). "Neutrophil gelatinase-associated lipocalin (NGAL), kidney injury molecule-1 (KIM-1), interleukin-18 (IL-18), and cystatin C (CysC) are some of the new biomarkers that have shown promise in early AKI detection and in differentiating structural from functional kidney injury." (PMID 40868897, 2025). "However, when AKD was evaluated incorporating Cystatin C, a more stable biomarker of glomerular filtration in the context of SCA, and markers of structural kidney injury were incorporated (i.e., macroalbuminuria, positive NGAL), AKD was identified as a risk factor for sMBD." (PMID 36819194, 2022). "Although novel, sensitive biomarkers for KI have emerged quickly, such as IL6, cystatin C, kidney injury molecule-1, NGAL, urine vanin-1, and liver fatty acid-binding protein, BUN and Scr are still the most utilized biomarkers to assess kidney injuries in experimental animal models." (PMID 32630021, 2020).
melanoma (17 papers, 2004 to 2025). A malignant, usually aggressive tumor composed of atypical, neoplastic melanocytes. "When melanoma cells were injected intravenously, cystatin C–deficient lungs showed reduced metastasis, but subcutaneous growth of melanoma cells was not different from that in control mice." (PMID 21085595, 2010). "Cathepsin L down-regulation also does not appear to be linked to expression of the cysteine protease inhibitor cystatin C. Cathepsin L does however make a significant contribution to B16F10 melanoma cell invasion, particularly through cell migration." (PMID 17488522, 2007). "Our conclusion from this data is that over-expression of cystatin C, while decreasing tumor burden, causes only modest increase in the survival of animals following tail vein injection of melanoma cells." (PMID 15904519, 2005). "In this study we show over-expression of cystatin C in melanoma cells is associated with reduced metastasis and increased apoptosis in lung tissues." (PMID 15904519, 2005). "Thus, cystatin C causes prolonged cell division leading to decreased proliferation of melanoma cells, and internalization seems to be a prerequisite for this effect." (PMID 33837649, 2021). "Subsequently, human cystatin C was stably expressed in SK-MEL-5 (SK-MEL-5-hcystatin C) melanoma cells, which were subsequently implanted subcutaneously into NSG-SGM3 and hCD34+ humanized mice." (PMID 41233352, 2025). "In the B16-F10 melanoma model, compared with adjacent normal skin tissue, cystatin C underwent moderate oligomerization during tumor progression." (PMID 41233352, 2025). "Single-cell RNA sequencing (scRNA-seq) data from 12 melanoma patients confirmed high CST3 expression within the myeloid cell compartment, as well as ectopic expression in the tumor compartment." (PMID 41233352, 2025). "Addition of cystatin C, a secreted cysteine protease inhibitor, to A375 melanoma cell cultures resulted in rapid decrease in cell numbers." (PMID 33837649, 2021). "Yet, the net effect on the cells following internalization was larger than seen for cystatin C, which was both internalized and endogenously expressed in the melanoma cells." (PMID 32810913, 2020). "Previous studies of effects on the cellular level by externally added type 2 cystatins have indicated growth promotion of fibroblasts by the chicken analogue to human cystatin C, but growth inhibition of melanoma cells by a recombinant snake venom cystatin." (PMID 32810913, 2020). "Preliminary experiments suggested that the melanoma-microglia cross-talk stimulated an enhanced secretion of the cysteine protease inhibitor Cystatin C (CysC) (unpublished)." (PMID 29722001, 2018). "In patients with melanoma, increased cystatin C serum levels correlated with the stage of disease were highest for metastatic melanoma patients." (PMID 28282874, 2017). "Along this line, a more elevated serum level of cystatin C has been also detected in patients with colorectal cancer and advanced melanoma than in patients with primary melanoma and healthy controls." (PMID 28282874, 2017). "Overexpression of cystatin C has been shown to inhibit the invasive potential of human melanoma and glioblastoma cell lines." (PMID 19956729, 2009). "We have shown cystatin C, a potent cathepsin L inhibitor, blocks motility and invasion of melanoma cells." (PMID 17488522, 2007). "In this work, expression of cystatin C fused to GFP also showed a dramatic inhibition of in vitro invasion of B16 melanoma cells." (PMID 15904519, 2005). "A cytoplasmic expression was noted for GFP alone and cystatin C-GFP fusion when transiently expressed in B16 melanoma cells." (PMID 15904519, 2005). "We have previously found cystatin C over-expression inhibits both melanoma cell migration and metastasis." (PMID 15904519, 2005). "Quantitation of apoptosis showed an average two-fold increase in apoptotic melanoma cells within lung tissue of animals injected with cystatin C over-expressing cells." (PMID 15904519, 2005).
melanoma (continued). "We believe cystatin C over-expression effects are primarily due to intracellular expression in our B16 melanoma cell model." (PMID 15904519, 2005). "To analyze the contribution of cysteine proteases to metastasis we have over-expressed in B16 melanoma cells the natural cysteine protease inhibitor, cystatin C. We measured in vitro invasion of cystatin over-expression clones with Boyden chamber type assays." (PMID 15904519, 2005). "The cystatin C-GFP fusion product that we introduced into B16 F10 melanoma allowed us to follow the distribution of metastatic cells in animals." (PMID 15904519, 2005). "The expression of cystatin C-GFP fusion was observed in B16F10 melanoma cells following transient transfection of plasmid construct DNA." (PMID 15904519, 2005). "We compared the subcutaneous growth of B16 melanoma control and cystatin C over-expressing clones in syngeneic C57 BL6 mice." (PMID 15904519, 2005). "In this work we demonstrate that apoptosis is increased in lung micrometastases when melanoma cell invasion is inhibited by cystatin C over-expression." (PMID 15904519, 2005). "The number of lung metastases following tail-vein injection were decreased, however growth of subcutaneous melanoma tumors over-expressing cystatin C was only slightly inhibited." (PMID 15904519, 2005). "We next examined the effect of cystatin C over-expression on survival of mice injected with B16F10 melanoma cells and found about a 10% increase in median survival time." (PMID 15904519, 2005). "Notably, CST3 was recently reported as a glucocorticoid response gene and can predict immunotherapy failure of patients with multiple cancers, including melanoma, possibly by directing recruitment of Trem2+ macrophages." (PMID 36969056, 2023). "Therefore, our results suggest that CST3 RES probably affected ICI treatment response in melanoma patients." (PMID 36969056, 2023). "Moreover, in vitro and in vivo experiments in immune-deficient mice bearing xenografts of human melanoma brain metastases showed that the extracellular cysteine protease inhibitor cystatin C is involved in the melanoma cell-microglia interaction." (PMID 36411434, 2022). "Cystatin C secretion is increased in both melanoma and microglial cells." (PMID 36411434, 2022). "Our results indicated that high levels of cystatin C could only be detected in the milieu of melanoma cells from primary lesions." (PMID 20684763, 2010). "We previously found cystatin C over-expression decreased B16 melanoma cell migration." (PMID 17488522, 2007). "We have found that cystatin C over-expression dramatically reduces melanoma cell invasion." (PMID 15904519, 2005). "Additional effects cystatin on melanoma cell metastasis might have been expected if our melanoma cystatin over-expressing clones had secreted cystatin C. Multiple roles extracellular cathepsin B have been suggested, including matrix degradation." (PMID 15904519, 2005). "Thus, increased apoptosis of lung metastasized B16 melanoma cells correlates with decreased tumor burden upon cystatin C over-expression." (PMID 15904519, 2005). "The point is, our results on melanoma metastasis may only pertain to intracellular over-expression of cystatin C." (PMID 15904519, 2005). "In cystatin C transfected B16 melanoma cells, the overexpression of inhibitor resulted in the inhibition of melanoma cell mobility and of the ability to penetrate artificial matrices by about 50%, as well as in the suppression of metastasis by at least 90%, compared to controls." (PMID 15138478, 2004). "For example, decreased levels of cystatin C have been correlated with better survival rates, as seen in a recent study for the prognosis and evaluation of renal cell carcinoma patients, while conversely enhanced levels of cystatin C were observed in patients with melanoma and CRC." (PMID 31212661, 2019).
melanoma (continued). "As far as the intracellular content of cystatin C was concerned, flow cytometry analysis revealed a modest, but significantly (p < 0.01) higher amount of this physiological cathepsin B inhibitor in cell lines from primary melanoma in comparison to those from metastatic lesions." (PMID 20684763, 2010). "To assess the role of tumor-derived cystatin C, we used the CRISPR-Cas9 system to generate a CST3-knockout B16-F10 melanoma cell line." (PMID 41233352, 2025). "Over-expression of cystatin C-GFP (c23, c28) decreased the invasion of B16F10 melanoma cells through Matrigel coated filters by about 90% relative to control G1 cells (GFP transfected)." (PMID 15904519, 2005). "In the melanoma lines where cystatin E/M was secreted, cystatin C was generally absent or expressed at a very low level." (PMID 20074384, 2010). "However, in the melanoma lines where cystatin E/M was secreted, cystatin C was generally absent (MCC13, MCC57 and MCC72) or expressed at a very low level (MCC70)." (PMID 20074384, 2010). "Finally, the inhibition of melanoma cell migration via down-regulation of cathepsin L appears to be independent of cystatin C expression." (PMID 17488522, 2007). "Similarly, sequence analysis of RT-PCR product revealed a signal peptide amino acid difference (-4 Ala→Gly) between Balb c (inserted cDNA) and B16 melanoma cystatin C messenger RNA (endogenous) (data not shown)." (PMID 15904519, 2005). "The melanoma cell density in the lung and melanoma distributions were similar for both GFP labeled and cystatin C-GFP clones (data not shown)." (PMID 15904519, 2005).
amyotrophic lateral sclerosis (16 papers, 2010 to 2025). Amyotrophic lateral sclerosis (ALS) is a neurodegenerative disease characterized by progressive muscular paralysis reflecting degeneration of motor neurons in the primary motor cortex, corticospinal tracts, brainstem and spinal cord. "A neuroprotective action of cystatin C has also been demonstrated in the amyotrophic lateral sclerosis mouse model and in the progressive myoclonic epilepsy type 1 mouse model." (PMID 39958955, 2025). "Although the use of CSF cystatin C as a biomarker for Amyotrophic Lateral Sclerosis (ALS) is controversial, research in this area continues." (PMID 37834128, 2023). "Recent studies have reported a significant reduction in cystatin C concentration in the CSF of patients with amyotrophic lateral sclerosis (ALS) and several other neurodegenerative diseases, relative to healthy controls." (PMID 23497730, 2013). "Cystatin C (CysC) levels in amyotrophic lateral sclerosis (ALS) have been found changes, however, the associations between serum CysC levels and the progression and survival of ALS remain largely unknown." (PMID 38249592, 2023). "Cystatin C plays a neuroprotective role in neurodegenerative diseases including PD, AD, amyotrophic lateral sclerosis (ALS), and subarachnoid hemorrhage (SAH)." (PMID 32438638, 2020). "We and others have reported that cystatin C levels are reduced in the CSF of patients with amyotrophic lateral sclerosis (ALS) when compared to both healthy controls and neurological disease controls." (PMID 23497730, 2013). "Research has shown that several serum oxidant factors may act as important biomarkers to predict the disease severity in neurodegenerative diseases, such as Parkinson’s disease (PD) and amyotrophic lateral sclerosis (ALS), including uric acid (UA), serum creatinine (Scr), and cystatin C (Cys-C)." (PMID 34566557, 2021).